STC2 (stanniocalcin 2)
Diseases named in the same sentence as STC2 in open-access papers (continued):
Sharing a sentence is not in itself a finding about the gene and the disease.
cancer (continued). "In conclusion, our study, along with existing research, positions STC2 as a gene of considerable interest in cancer biology." (PMID 40535801, 2025). "Our pan-cancer analysis established STC2's involvement in various cancer types, underscoring its potential as a universal biomarker." (PMID 40535801, 2025). "Future studies should focus on validating these potential targets and exploring the mechanistic roles of STC2 in cancer biology to fully exploit its therapeutic potential." (PMID 40535801, 2025). "Stanniocalcin-2 (STC2) is a secreted glycoprotein that has been shown to play a role in the development of cancer through its upregulation." (PMID 40143207, 2025). "We identified Stanniocalcin-2 (STC2) as a key regulator in CRC, associated with poor prognosis, survival outcomes and cancer cell proliferation or invasion." (PMID 40535801, 2025). "In usnic acid-treated cancer cells, the STC2 gene expression level increased 3.1-fold according to the transcriptome data, and a 4.2-fold increase was confirmed by the qRT-PCR results compared to the control MDA-MB-231 cells." (PMID 41226241, 2025). "According to spatial transcriptomic analysis of CRC tissues, STC2 expression was primarily found in malignant tumor regions and was substantially positively correlated with malignant cells in several CRC samples, including liver metastases." (PMID 41502509, 2025). "Firstly, we employ Cancer Cell Line Encyclopedia datasets to study the relative expression of STC2 in different types of cancer cell lines." (PMID 40535801, 2025). "High STC2 expression predicted poor survival outcomes in several cancer types, reinforcing its prognostic relevance." (PMID 40535801, 2025). "The correlation between STC2 expression and patient survival events in pan-cancer analysis is particularly interesting." (PMID 40535801, 2025). "This study provides valuable insights into the oncogenic role of STC2, proposing it as a promising target for therapeutic intervention and a marker for aggressive cancer phenotypes." (PMID 40535801, 2025). "We observed a significant positive correlation between STC2 and a wide range of immune checkpoint genes across various cancer types." (PMID 38229155, 2024). "Among the most significantly upregulated genes, we identified common biomarkers in human cancers: STC2, CACNA1C, and GAGE2A." (PMID 38493239, 2024). "Although the receptor of STC2 and its downstream signalling remain to be dissected, our current findings support a model that STC2 switches cancer cells’ priority from proliferation to survival, hence facilitating cellular adaptation to nutrient insufficiency." (PMID 39107307, 2024). "Although the receptor of STC2 and its downstream signaling remain to be dissected, our current findings support a model that STC2 switches cancer cells’ priority from proliferation to survival, hence facilitating cellular adaptation to nutrient insufficiency." (PMID 38464261, 2024). "Biologically, STC2 induction and secretion promote cell survival but attenuate cell proliferation during nutrient insufficiency, thus switching the priority of cancer cells from proliferation to survival." (PMID 38464261, 2024). "The expression level of STC2 is upregulated in gastric tissues, and STC2 as an independent factor in cancer elevates lymphatic metastasis and venous invasion in GC." (PMID 38001121, 2023). "We investigated the single nucleotide variations (SNVs) of HFRS genes in different cancers and observed that some genes (CCT6A, TF, KRT14, P4HA2, PGK1, SLC16A2, and STC2) were frequently mutated in COAD, STAD, UCEC, and SKCM." (PMID 36998462, 2023). "Compared with those in other cancer types, the lowest correlation between STC2 expression and DNAss (R = −0.47, p < 0.001), EREG-METHss (R = −0.48, p < 0.001), DMPss (R = −0.43, p < 0.001) and ENHss (R = −0.55, p < 0.001) were found in TGCT." (PMID 36685853, 2022).
cancer (continued). "In conclusion, we explored the effect of PM2.5 on tumorgenesis, identified the regulated key gene STC2, and then systematically analyzed the pan-cancer information of multiple databases." (PMID 36685853, 2022). "We next investigated the potential association between the infiltration level of immune cells and STC2 gene expression in diverse cancer types by using TIMER." (PMID 36685853, 2022). "Immunohistochemistry results showed that STC2 staining of the lymph node metastatic and primary cancer tissues was obviously stronger than that of normal tissues." (PMID 33797657, 2022). "In the progression of COAD, STC2 contributed to cancer cell metastasis by promoting epithelial–mesenchymal transition." (PMID 35937984, 2022). "The prognostic significance of STC2 in different cancers was evaluated using Cox regression analyses of the TCGA database." (PMID 35937984, 2022). "Recent studies have demonstrated that STC2 is associated with cell proliferation, EMT, and clinical progression in a variety of cancers." (PMID 33797657, 2022). "The expression of STC2 in cancer tissues was higher than in the corresponding normal tissues (P < .001)." (PMID 35945754, 2022). "Next, we investigated the relationship between STC2 expression and clinical features in various cancers, including age, gender, stage, grade and TMN staging in patients with tumors." (PMID 36685853, 2022). "Due to the importance of STC2 in cancer development and the imperfection of the previous studies, our experiment verified STC2 influence on the invasion ability and metabolism reprogramming in NPC and found a new pathway involved." (PMID 33797657, 2022). "Our analysis of the relationship between STC2 expression and cancer stemness identified a positive correlation between STC2 expression and DNAss、EREG-METHss and ENHss in KIPAN." (PMID 36685853, 2022). "According to the data from the TCGA database, STC2 exhibited inconsistent expression across 26 types of human cancer." (PMID 36685853, 2022). "The results revealed that the expression level of STC2 was significantly up-regulated in most cancers." (PMID 35937984, 2022). "For TMN staging, the differential expression of STC2 was related to T stage in 15 types of cancer, including STES, KIRP, HNSC, and THCA." (PMID 36685853, 2022). "Abnormal expression of STC2 promoted the growth, invasion, and colony formation of cancer cells, whereas silencing STC2 delayed the cell cycle in the G0/G1 phase." (PMID 36698399, 2022). "The results of Pearson analysis confirmed that STC2 expression level was significantly and positively correlated with DNA repair genes in most types of cancer." (PMID 35937984, 2022). "The expression of STC2 is strongly correlated with the development of human cancers and is a prognostic marker of renal, breast, and ovarian cancers." (PMID 35102149, 2022). "The STC2 expression was lower in KIRP in cancer versus adjacent normal tissues, and significantly higher in another cancers except for CESC, LUAD, PRAD, PAAD, PCPG, and BLCA (p > 0.05)." (PMID 36685853, 2022). "STC2 is highly expressed in various cancer tissues and promotes the growth, migration, and invasion of cancer cells." (PMID 36496076, 2022). "This review focuses on discussing the regulation, biological functions and clinical importance of STC2 in human cancers." (PMID 35501821, 2022). "We investigated the relationship between immune cell infiltration and STC2 gene expression in different cancer types, and found that STC2 expression was significantly correlated with the level of immune cell infiltration." (PMID 36685853, 2022). "A significant positive correlation between the expression level of STC2 and the expression levels of immune checkpoint genes was observed in most cancers in our study." (PMID 35937984, 2022). "Differences of STC2 expression were also observed in N stage and M stage across the cancers, nine types of cancer in N stage and only three types of cancer in M stage." (PMID 36685853, 2022).
cancer (continued). "This review focuses on discussing the regulation, biological importance and particularly, the potential clinical utilization of STC2 in the field of human cancers." (PMID 35501821, 2022). "The knockdown of STC2 reduced the expression, and vice-versa, the overexpression promoted the cancer cell growth and proliferation." (PMID 34612765, 2021). "In the future studies, serum STC2 from various malignancies can be compared to determine in which cancer it is elevated remarkably and stably, that is to say, great potential in diagnosis." (PMID 34612765, 2021). "The aberrant STC2 expression has significant consequences for the prediction, incidence, metastasis, and prognosis of different cancers, including various cancers of the liver, colon, and prostate." (PMID 34337075, 2021). "STC2 is a secretory glycoprotein hormone that can regulate cell proliferation and cancer cell lesions." (PMID 34225733, 2021). "More studies regarding the significance of secretory STC2 in cancer will be reviewed in subsequent section." (PMID 34612765, 2021). "The altered expression of STC2 has been observed in numerous cancers and possessed predictive value for patient survival." (PMID 34612765, 2021). "The involvement of IGFBP1, TIMP1, SPP1, IGFBP3, and STC2 in mediating chemotherapy resistance in various cancers have been extensively studied." (PMID 34737677, 2021). "Role of STC2 in human cancers has been studied from two different perspectives namely expression of STC2 in specific cancer models and cell lines, and STC2's function in cell growth, differentiation and apoptosis." (PMID 32296395, 2020). "The aberrant expression of STC2 promoted cancer cell growth, invasion, and colony formation while silencing STC2 delayed the cell cycle in G0/G1 phase." (PMID 32258098, 2019). "STC2 is an oncogenic gene that promotes cancer metastasis and epithelial-mesenchymal transition in cancers, and the induction of oxaliplatin resistance in colorectal cancer." (PMID 30139993, 2018). "Given STC1’s role in calcium and phosphate metabolism, STC2 was first investigated for its putative action on phosphate metabolism and cancer metastasis, but it was later found that STC2’s main role is as a component of GH-IGF axis." (PMID 29280739, 2017). "Previous studies have demonstrated that overexpression of STC2 increases cancer cell migration and motility and is correlated with metastatic spread in cancer tissue." (PMID 27863406, 2017). "The HRO data set documented gains of STC2 in 8 HRO cancer tissues, of which 5 harboured gains of VCAN as well." (PMID 28486536, 2017). "It is reported that STC2 is highly expressed in many human cancer tissues compared with the relevant normal tissues, which is possibly responsible for poor prognostic outcome." (PMID 29207625, 2017). "These genes include LRAT, MEIS1, ST8SIA1 and STC2 which have all previously been shown to be subject to transcriptional downregulation as an effect of DNA hypermethylation in human cancers." (PMID 28931069, 2017). "The STC2 expression level (low expression versus high expression) was further shown to correlate with cancer clinicopathological information of CRC patients." (PMID 27662663, 2016). "The area under the ROC curve was 0.968 (P < 0.001), which indicated that serum STC2 is sensitive and specific to differentiate healthy individuals and cancer patients." (PMID 27662663, 2016). "STC2 is a target gene of hypoxia-inducible factor-1, which stimulates the proliferation of cancer cells during hypoxic conditions." (PMID 24743310, 2014). "In contrast to STC1, STC2 has been consistently found to have an anti-apoptotic role in cancer cells." (PMID 24743310, 2014). "Both STC1 and STC2 are considered to be promising biomarkers, because their mRNA levels are elevated in the PB of cancer patients." (PMID 24743310, 2014).
cancer (continued). "Some mechanistic and functional studies have showed that STC2 expression is induced by hypoxia and contributes to the suppression of apoptosis and survival of cancer cells." (PMID 24743310, 2014). "Such a broad impact suggests that STC2 may serve as a universal marker for aggressive cancer phenotypes and could be a target for therapeutic intervention." (PMID 40535801, 2025). "Stalcitin 2 (STC2) is a secreted glycoprotein that regulates the progression of malignant tumors." (PMID 41425852, 2025). "This downregulation of STC2 supports the hypothesis that STC2 may contribute to chemoresistance in cancer therapy." (PMID 40006048, 2025). "The significant suppression of STC2 expression following Dox treatment suggests that the drug may counteract the protective effects of STC2, therefore sensitizing cancer cells to apoptosis." (PMID 40006048, 2025). "Given the significant roles of STC2 in CRC and potentially other cancers, targeting STC2-related pathways might offer new therapeutic opportunities." (PMID 40535801, 2025). "Transfection of STC2 siRNAs significantly leads the reduction of cancer cell function." (PMID 40535801, 2025). "Given that our data and previous reports suggest STC2 is an estrogen-regulated protein, it is plausible that Dox disrupts the ER signaling pathways that typically drive STC2 overexpression in cancer cells, leading to the downregulation of estrogen-responsive genes, including STC2." (PMID 40006048, 2025). "Therefore, STC2 can be regarded as a prognostic biomarker and a promising therapeutic target for cancer treatment." (PMID 38464261, 2024). "Finally, we analyzed the relationship between STC2 and pan-cancer as well as various clinical factors using large databases." (PMID 39119088, 2024). "It is an interesting question regarding the roles of STC2 in non-cancer cells." (PMID 39107307, 2024). "Taken together, our findings indicate that nutrient insufficiency induces STC2 expression, which in turn governs the adaptation of cancer cells to nutrient insufficiency through the maintenance of redox homeostasis, highlighting the potential of STC2 as a therapeutic target for cancer treatment." (PMID 38464261, 2024). "To acquire a more comprehensive understanding of the ER stress related gene STC2 in cancer development and immunity, we performed a pan-cancer analysis to investigate the aberrant expression of STC2 across 33 different cancer types in the TCGA-Pan-cancer cohort." (PMID 38229155, 2024). "STC2 expression trends in pan-cancer has been explored further." (PMID 38460960, 2024). "Taken together, our findings indicate that nutrient insufficiency induces STC2 expression, which in turn governs the adaptation of cancer cells to nutrient insufficiency through the maintenance of redox homoeostasis, highlighting the potential of STC2 as a therapeutic target for cancer treatment." (PMID 39107307, 2024). "The results demonstrated that the expression of STC2 was related to TMB in six types of cancers, including CESC (R = 0.13, p = 0.03), LUAD (R = 0.15, p = 0.001), THYM (R = 0.29, p = 0.001), READ (R = 0.25, p = 0.02), BRCA (R = −0.11, p = 0.001), and ESCA (R = −0.15, p = 0.04)." (PMID 36685853, 2022). "The expression of STC2 is elevated in several types of cancers, including neuroblastoma, prostate, ovarian, and colon cancer, suggesting its potential role in development and progression of cancers." (PMID 35790735, 2022). "In pan-cancer analysis, STC2 was upregulated in 20 cancers and downregulated in seven cancers." (PMID 35937984, 2022). "Several reports suggest elevated expression of STC2 in cancer." (PMID 35790735, 2022). "For STC2, it was recognized as a regulator in CC cell biological processes, and silencing STC2 could effectively suppress cancer cell proliferation, survival, and migration." (PMID 35734431, 2022).
cancer (continued). "However, the effects of STC2 on cancer development and progression across pan-cancer are not yet completely known." (PMID 35937984, 2022). "To explore the role of PM2.5-regulated STC2 in different cancers, we analyzed STC2 expression." (PMID 36685853, 2022). "The association between STC2 and TMB was significant in 15 cancer types." (PMID 35937984, 2022). "Other microRNAs are also found to regulate STC2 expression in human cancers." (PMID 35501821, 2022). "In addition, STC2 plays an important role in the development of cancers, including hepatocellular carcinoma, head and neck squamous cell carcinoma, lung cancer, laryngeal squamous cell carcinoma, breast cancer, and ovarian cancer." (PMID 33797657, 2022). "Previous studies have shown that STC2 is overexpressed in several cancers with poor prognosis." (PMID 35719372, 2022). "Studies have demonstrated that STC2 is oncogenic in several forms of cancer." (PMID 34337075, 2021). "In addition, many researchers drew the conclusion that STC2 has connection with the occurrence and metastasis of many cancers, and also serves as an effective biomarker in some cancers." (PMID 37287492, 2021). "STC2 plays an important role in the regulation of the proliferation and apoptosis of cancer cells." (PMID 32906580, 2020). "The action mechanism of STC2 in the cancer has been explored." (PMID 32579175, 2020). "Interestingly, growing evidence demonstrated that STC2 was induced in most human cancer tissues by hypoxic stress and endoplasmic reticulum(ER) stress in cancer microenvironment." (PMID 29207625, 2017). "The mammalian peptide hormone stanniocalcin 2 (STC2) plays an oncogenic role in many human cancers." (PMID 27863406, 2017). "More importantly, STC2 has been reported to involve in progression of many cancers." (PMID 27662663, 2016). "These investigations suggest that STC2 has a close relationship with several types of cancer." (PMID 27662663, 2016). "Meanwhile our data suggest that STC2 could impact adjacent epithelia or cancer cells by a paracrine way." (PMID 27662663, 2016). "But the molecular mechanism of STC2 on cancer cell behaviors is still poorly discovered." (PMID 27662663, 2016). "The STC2 protein involves in carcinogenesis and progression of many cancers." (PMID 27662663, 2016). "Aberrant expression of STC1 or STC2 correlates with poor prognosis in multiple types of cancer." (PMID 24743310, 2014). "The expression of STC2 has been reported to be highly correlated with human cancer development." (PMID 23548070, 2013). "Whether STC2 is protective in nature is still unclear since studies have shown it has both protective and detrimental roles in cancer progression in vitro." (PMID 21545732, 2011). "As such, it is hypothesized that STC2 is a critical contributor for the development of acquired resistance to chemo- and radio- therapies, thus holding the promise to be a universal therapeutic target for multiple types of cancers." (PMID 35501821, 2022). "As a secreted glycoprotein hormone, serum STC2 levels can be easily monitored, thus it is promising to investigate whether serum STC2 levels can be utilized as a practical biomarker to assess prognosis or recurrence in patients with various types of cancers." (PMID 35501821, 2022). "Meanwhile, the expression of STC2 was associated with ploidy in 10 cancer types, with positive correlation in seven cancer types and negative correlation in three cancer tpyes, such as STAD (R = 0.11, p = 0.03), HNSC (R = 0.16, p < 0.001), MESO (R = −0.30, p = 0.001) and TGCT (R = −0.27, p = 0.001)." (PMID 36685853, 2022). "Additionally, a series of recent studies identify STC2 to be involved in cancer development." (PMID 35790735, 2022). "However, the clinical significance and the mechanism by which STC2 plays a role in cancer remain unclear and need to be further elucidated." (PMID 35790735, 2022).